TIGIT (T cell immunoreceptor with Ig and ITIM domains)
Diseases named in the same sentence as TIGIT in open-access papers (continued):
Sharing a sentence is not in itself a finding about the gene and the disease.
tumor (continued). "Considering all these results, it is possible to speculate that later than tumorigenesis, when the tumor already presents an immune infiltrate, immune cells, particularly T cells, upregulate TIGIT, promoting an immunosuppressive microenvironment that leads to metastasis and unfavorable prognosis." (PMID 35656508, 2022). "In addition, the result of the TIGIT blockade is an activation of tumor-activated CD8+ TILs." (PMID 36497240, 2022). "In this regard, the effect of blocking TIGIT on elevated tumor-infiltrating CD3+ cells should be scrutinized in detail: Thus, it could be reasoned that blocking TIGIT affects primarily immune suppressive T cells such as Tregs, more than affecting the functionality of CD8+ cytotoxic T cells." (PMID 36551992, 2022). "However, tumor tissue exhibited strong communication in CCLs, CXCLs, and TIGIT signaling pathways." (PMID 35812401, 2022). "By interacting with ligands with its ligands CD155, PVRL3, and CD112, TIGIT blocks NK cell-mediated tumor killing, activates immunosuppressive DCs, decreases CD8 T-cell initiation and differentiation, and inhibits CD8 T cell-mediated tumor killing, thus causing immunosuppression." (PMID 36119533, 2022). "Thus, TIGIT is a marker of exhausted T cells in the tumor microenvironment, and its targeting by therapeutic antibodies could reverse T and NK cell exhaustion." (PMID 36544779, 2022). "Indeed, tumor-infiltrating NK cells are found to express high levels of TIGIT." (PMID 35464486, 2022). "The purpose of this review is to update the role of TIGIT in cancer progression, looking at last year’s studies about its pathways that are often upregulated in immune cells and possible therapeutic strategies to avoid tumor aggressiveness, drug resistance, and treatment side effects." (PMID 35656508, 2022). "It is involved with a variety of cancer-associated functions, including the intrinsic activity of tumor cells that regulate proliferation, adhesion, and migration, as well as the ability to influence the immune response by binding to the immunomodulatory receptors dNaM-1, CD96, and TIGIT." (PMID 35768666, 2022). "However, TIGIT blockade monotherapy shows minimal effects on controlling tumor growth." (PMID 36377656, 2022). "Therefore, an accurate assessment of the intra-tumor T cell expression of TIGIT along with that of CD226, which directly competes for the binding to CD155, is critically required at the single patient level to fully take advantage from PARPi-mediated increase in CD155 expression on tumor cells." (PMID 36428727, 2022). "Since TIGIT could act as a negative regulator of NK cell functions, it represents an ideal molecule that can be targeted in checkpoint blockade strategies to boost NK tumor-immunity against CD155/PVR expressing cancers." (PMID 36291830, 2022). "Collectively, these findings may suggest a novel hypothesis that TIGIT may be a better IC to target in OAC than PD-1 to reinvigorate anti-tumour immunity but to also reduce the survival of OAC cells under the nutrient-deprived and hypoxic conditions of the hostile TME." (PMID 35245832, 2022). "Therefore, it will be of great interest and importance to investigate the potential for targeting TIGIT both as a tumor-intrinsic factor and as a tumor-extrinsic factor using antibody-based immunotherapy to prevent TIGIT-mediated T-cell suppression and immune escape." (PMID 36163179, 2022). "Similarly to the CTLA-4/CD28 dynamic, TIGIT outcompete DNAM-1 (CD226) and CD96 for the binding of CD155, impeding DNAM-1 positive co-stimulation and delivering a direct inhibitory signal as shown in TIGIT-deficient mice with delayed tumor growth." (PMID 34572799, 2021). "Some potential predictive biomarkers have been identified up to now, such as tumor mutational burden (TMB), mismatch repair deficiency (dMMR), immune cell infiltration, and inhibitory receptors related gene expression such as PD-1, PD-L1, CTLA-4, LAG-3, TIM3, and TIGIT." (PMID 34367952, 2021).
tumor (continued). "Anti-PD-1 and anti-TIGIT dual immune checkpoint treatment in murine intracranial tumors has synergistic effects in enhancing antitumor functions of effector T cells and decreasing suppressive tumor-infiltrating DCs and Tregs, thereby conferring significant survival benefit." (PMID 34359588, 2021). "Our results have indicated that the high expression of TIGIT might not be statistically associated with poor tumor differentiation and increased tumor size (both p-values > 0.05)." (PMID 34638729, 2021). "This suggests that TIGIT expression is induced specifically in the tumor by yet unknown mechanisms." (PMID 34102454, 2021). "A recent research reported that TIGIT could be a promising new target for tumour immunotherapy." (PMID 34841705, 2021). "Interestingly the anti-TIGIT antibody with a combination of PD-1 blockade could improve the efficacy of the anti-tumor treatment representing a promising clinical therapeutic strategy." (PMID 34829838, 2021). "However, a study in which different T-cell subsets were depleted by specific antibodies found that CD8+ T cell depletion as well as Treg depletion could abrogate the anti-tumor effects of TIGIT-blockade in a mouse cancer model." (PMID 34367161, 2021). "However, expression of the TIGIT checkpoint proteins on immune cells were decreased after PBC treatment in the MB49 vs. MBT-2 model, and the authors suggest that TIGIT may play a role in the diverse anti-tumor responses between models." (PMID 33802033, 2021). "TIGIT expression was found to be higher in the cells within tumor microenvironment than in those in the periphery, which could theoretically mean that using anti-TIGIT monoclonal antibody would provide a more specific targeted immunotherapy with less autoimmune-related toxicities." (PMID 34572799, 2021). "Furthermore, blocking TIGIT/PVR interaction with antibodies could induce anti-tumor effects by promoting tumor infiltration and restoring CD8+ T cell function." (PMID 34659197, 2021). "Moreover, we analyzed the correlation among four-gene signature (FeSig) (BID, TAZ, MT1G, and SLC7A11), downstream hub genes (CPNE7, WNT10B, ADAMTS14, and RUFY4), and immune checkpoints (PD-1, CTLA4, LAG3, and TIGIT) to further discover potential molecular mechanisms of tumor immunity." (PMID 34367965, 2021). "In CRC their expressions are strongly correlated with each other and, along with TIGIT and BTLA, are tightly associated with markers of T lymphocytes and cNK cells, in which they can inhibit receptor dependent activation, thereby dampening anti-tumor effector functions." (PMID 34975867, 2021). "Similarly, the blockade of TIGIT using antibodies unleashed NK cell and T cell anti-tumor function." (PMID 34885076, 2021). "Finally, the Tregs in the periphery compromised 9.59 ± 4.30% of the CD4+ T-cells, were characterised by high levels of TIGIT and ICOS expression albeit at lower levels compared to their tumour-associated counterparts (~30% higher median expression, respectively)." (PMID 33917832, 2021). "Alternatively, if PD-1 and TIGIT expressed on chronically activated Treg present within the tumor micro-environment both contribute to their strong suppressive capacity, PD-1 blockade may synergize with TIGIT-blockade in reducing local immune-suppression exerted by tumor-infiltrating Treg functions." (PMID 34367161, 2021). "Collectively, these data suggest that mRNA levels of VISTA, TIGIT and KLRG1 in CRC tumor tissues could be elevated in CRC patients with high grades of tumor budding, which is considered as a risk factor for poor disease prognosis and metastasis in CRC patients." (PMID 32393998, 2020). "In addition, the notable presence of TIGIT and its association with other immunosuppressive markers such as CD163 and PDL-1 suggest its possible role as a novel biomarker of an immunosuppressive tumor microenvironment in GBM." (PMID 32899203, 2020). "Quite different from that, liothyronine could exert anti-tumor effects by TIGIT/PVR blockade." (PMID 32894141, 2020).
tumor (continued). "Consequently, the engineering of a stimulatory CAR that incorporates the DNAM‐1 or TIGIT targeting domain could serve as an alternate strategy to target tumour cells." (PMID 32544282, 2020). "The OS T-reg cells expressed the canonical gene signature including the FOXP3 and IL2RA, and they also showed relatively high immune-inhibitory molecules including the CTLA4 and TIGIT, which may contribute to T-reg cell-mediated suppression of anti‐tumor immune responses in OS lesions." (PMID 33303760, 2020). "Another possible explanation is that both co-inhibitory receptors, PD-1 and TIGIT, perhaps participate in orchestrating thymic development in the WT animals and influence the elimination of T cells that react to autoantigens which potentially include “altered self” tumor neo-antigens." (PMID 33117369, 2020). "Therefore, the authors suggest that TIGIT expression on NK cells could be associated with activated and functional status of NK cell in AML and may impede tumor progression." (PMID 33304346, 2020). "Therefore, regarding the distinct roles of TIGIT in tumor initiation and progression, the use of checkpoint inhibitors at different disease stages might lead to opposing effects." (PMID 30644386, 2019). "Despite efficacy in pre-clinical tumour models, whether individual blockade of TIGIT or in combination with other checkpoint therapies can enhance NK cell effector function for the generation of effective anti-tumour response in human cancer patients remains to be demonstrated." (PMID 30626155, 2019). "Thus, neutralizing TIGIT/CD96 alone or in combination with other agents might be a potential strategy to improve anti-tumor immunotherapy by NK cells." (PMID 31340613, 2019). "In BABL/c nude mice and CD8+ T cell depleting mice, the tumor growth inhibition caused by TIGIT knockout could not be entirely rescued in the absence of CD8+ T cells." (PMID 30555485, 2018). "Therefore, we propose that tumor intrinsic TIGIT may deliver inhibitory signals to CD8+ T cells and NK cells by engaging with PVR." (PMID 30555485, 2018). "In conclusion, tumor-intrinsic TIGIT could suppress the function of both NK cells and CD8+ T cells." (PMID 30555485, 2018). "Importantly, the expression of TIGIT appears to be higher in the cells within tumor microenvironment than in those in the periphery, which would theoretically offer the advantage of a more targeted-directed therapy with less systemic autoimmune-like toxicities." (PMID 29544515, 2018). "Therefore, the antibody-mediated TIGIT blockade could inhibit MC38 tumor growth through blocking TIGIT expressed on tumor cells." (PMID 30555485, 2018). "Moreover, IFN-γ production by CD8+ T cells of tumor-draining lymph node and spleen increased along with the inhibition of tumor growth caused by TIGIT blockade with α-TIGIT but not by PVR protein." (PMID 30555485, 2018). "Additionally, TIGIT positive tumor infiltrating CD8 T-cells could be detected in other solid-tumor entities such as small-cell lung carcinomas and colorectal carcinomas." (PMID 28073373, 2017). "Similarly, TIGIT has an opposite effect to DNAM-1 on tumor immunity." (PMID 27049654, 2016). "Reduction in mean fluorescence intensities (MFI) of LAG3, TIGIT and TIM3 in CD8+ tumor infiltrating lymphocytes of dual PI3Kγ/PD-L1 treatment was observed." (PMID 41431358, 2026). "Secondly, we showed that tumor control by co-targeting PD-L1 and TIGIT can be further enhanced by additionally blocking VEGF, a key player in tumorigenesis and tumor angiogenesis, in preclinical studies." (PMID 41613119, 2026). "In their study, the proportions of TIGIT+CD3+, TIGIT+CD4+, and TIGIT+CD8+ T cells in the peripheral blood of CRC patients were higher than in healthy donors, and these subsets were even more enriched in tumor tissue than in matched blood samples." (PMID 41596586, 2026).
tumor (continued). "Through multiple downstream mechanisms, the TIGIT/CD155 interaction suppresses the function of T cells and NK cells, thereby attenuating antitumor immunity and promoting tumor development and progression." (PMID 41596586, 2026). "An important limitation of this study is that TIGIT and CD155 were quantified in whole-tissue homogenates, which integrate signals from tumor cells, stromal elements, and multiple immune cell subsets." (PMID 41596586, 2026). "TIGIT is another emerging checkpoint that inhibits T-cell activation by binding to CD155 and CD112 on tumor cells and APCs." (PMID 41394868, 2025). "Specifically, TIGIT and PD-1 were upregulated, while CD226 was downregulated on NK cells, contributing to NK cell dysfunction and tumor immune evasion." (PMID 40231264, 2025). "Taken together, this analysis shows a mixed phenotype, as potentially tumor-induced immunosuppressive molecule such as CD73 is upregulated in peripheral T cells, whereas others, such as TIGIT and KLRG1, are reduced in NSCLC BM patients." (PMID 40346687, 2025). "Collectively, the evidence suggests that elevated TIGIT expression in ECCA correlates with poorer prognosis, likely facilitating tumor immune escape by reverting T cell exhaustion and amplifying immunosuppressive pathways." (PMID 39939322, 2025). "In line with our data, high expression of TIGIT and PVRIG on cytotoxic NK cells has been recently described as sign of exhaustion in NK cells infiltrating primary tumor sites." (PMID 40274631, 2025). "Our results show that strategically targeting TIM3, LAG3, TIGIT, CTLA4, IFITM, TREM2 and PD-1 in MMRd and also MMRp CRC tumors not only further limits tumor growth but can also significantly increase the complete elimination of tumors." (PMID 40027748, 2025). "It is well established that the anti-tumor activity of elraglusib (9-ING-41) involves the downregulation of the expression of several IC molecules, including TIGIT, and inhibition of glycogen synthase kinase-3 (GSK-3)." (PMID 40890162, 2025). "TOX is a positive regulator of PD-1, TIM3, TIGIT, and CTLA-4 expression in tumor-infiltrating CD8+ T cells." (PMID 40075727, 2025). "Then, it is revealed that Plac1+ tumor cells recruit CD4+ T cells via CXCL11/CXCR3 and induce Treg differentiation via PVR/TIGIT, which in turn activates the tumorigenic signaling of Plac1+ tumor cells via LTA/LTBR and forms a reciprocal protumor loop." (PMID 40056047, 2025). "TIGIT interacts with two primary ligands, CD155 and CD112, which are expressed on APCs or tumor cells." (PMID 41233805, 2025). "An analysis of these immune checkpoints in tumor and normal samples revealed significant differences in the expression of CD200, CD274, TIGIT, TNFRSF25, and TNFSF15 between the two groups (P < 0.05)." (PMID 40666524, 2025). "On the other hand, there are significantly upregulated inhibitory genes e.g. TIGIT that interacting with CD155 on antigen presenting cells and on tumor cells also in MM, is able to downregulate T and NK cell functions." (PMID 40079005, 2025). "Based upon our observations, we next investigated the impact of targeting T cell checkpoints on tumor growth by using anti-TIM3, anti-TIGIT, anti-LAG3, or anti-CTLA4, alone or in combination with anti-PD-1." (PMID 40027748, 2025). "Our immunohistochemistry studies confirmed that PD-L1 is expressed both in tumor and infiltrating cells, while CTLA-4, PD-1, PD-L1, TIM-3, TIGIT, and VISTA were identified in infiltrating cells, both intratumorally and peritumorally." (PMID 40565313, 2025). "Numerous transcripts related to immunological checkpoints, including SIGLEC15, PDCD1LG2 (PD-L2), TIGIT, PDCD1 (PD-1), CD274 (PD-L1), CTLA4, LAG3, and HAVCR2 (TIM3), are integral to tumor immune evasion mechanisms." (PMID 41194934, 2025). "Blockade of TIGIT ± CD39 blockade was able to restore effector function of CD8+ T cells and NK cells and significantly increased lysis of tumor cells." (PMID 40274631, 2025).
tumor (continued). "In melanoma, Tregs exhibit an elevated TIGIT/CD226 ratio, correlating with higher tumor-infiltrating Treg levels and worse clinical prognosis." (PMID 40723878, 2025). "Other inhibitory receptors expressed in tumor-infiltrating NK cells include LAG-3, TIM-3, and TIGIT." (PMID 40299429, 2025). "In the tumor microenvironment (TME), exhausted CD8+ T cells (Tex) simultaneously overexpress PD-1, TIM-3, LAG-3, and TIGIT." (PMID 40821806, 2025). "A study used mathematical modeling to explore the effects of inhibiting TIGIT, PVRIG, PVR, or their combinations on receptor engagement in immunological synapses (IS) between T-cells and tumor cells." (PMID 40567374, 2025). "T cell immunoglobulin and ITIM domain (TIGIT), an Ig superfamily member specifically expressed in immune cells, binds CD155 on tumor cells, directly inhibiting effector CD8+ T cell function." (PMID 41268548, 2025). "Other tumor evasion mechanisms include shielding via platelets or collagen, and upregulation of ligands such as CD155, which binds TIGIT on NK cells, impairing their function." (PMID 41246357, 2025). "Research indicates that TIGIT cooperates with HIF1-α to enhance tumour cell invasiveness, colony formation and angiogenesis, and subsequently promotes tumour development and progression." (PMID 40994140, 2025). "TIGIT was identified in 2009 as a member of the poliovirus receptor-related (PVR)-like protein family and has been shown to play a central role in tumor immunity and is a promising target in immunotherapy." (PMID 40890162, 2025). "Targeting the interaction between inhibitory receptors, such as TIGIT and NKG2A, and their ligands has the potential to offer novel therapeutic strategies that enhance NK cell antitumor activity and mitigate tumor metastasis." (PMID 40463500, 2025). "MPE T cells exhibited lower levels of co-inhibitory receptors (PD-1, LAG-3, TIGIT, TIM-3) expression relative to tumor." (PMID 41415427, 2025). "In conclusion at least one target molecule of the TIGIT/PVRIG pathway axis or the CD39/CD73 purinergic pathway was more frequently and at a higher MFI expressed in each tumor entity (BC: PVRIG, CD73; PC: TIGIT, CD39; NSCLC: CD73; MM: TIGIT, PVRIG, CD39)." (PMID 40274631, 2025). "PSMB9 displayed strong correlations with classical inhibitory molecules such as LAG3, PDCD1, CTLA4, TIGIT, HAVCR2, SLAMF7, and PD-L1 across nearly all tumor types." (PMID 41020834, 2025). "In contrary we found upregulated (EOMES, TNFSFR9, TIGIT, KLRD1) and downregulated genes (PAG1, GNLY, ANXA1, FGFBP2) that are involved in tumor escape from immune surveillance by suppressing T-cells or by reprogramming T-cells toward T-cell exhaustion." (PMID 40079005, 2025). "Targets such as TIGIT, VISTA, and B7-H3 are being investigated for their roles in immune regulation and tumor progression." (PMID 40870970, 2025). "Mechanistically, platelet-tumor cell adhesion induces transcriptional activation of CD155 in CTCs, facilitating TIGIT-mediated NK cell exhaustion through sustained receptor-ligand engagement." (PMID 40514754, 2025). "Pro-tumor elements, such as regulatory T cells (Tregs) and MDSCs, create an immunosuppressive environment, inhibiting anti-tumor immunity via cytokines (TGF-β and IL-10) and immune checkpoint molecules (PD-L1, CTLA-4, TIM-3, TIGIT, and NRP1)." (PMID 40908470, 2025). "TIGIT binds to CD155, an overexpressed ligand in tumor and stromal cells within the TME, transmitting inhibitory signals through its immunoreceptor tyrosine-based inhibitory motif (ITIM)." (PMID 40567374, 2025). "The association with IGSF8 may support immune cell recruitment and activation at inflammatory or tumor sites, whereas negative associations with CTLA4 and TIGIT imply a counter-regulatory effect on checkpoint pathways, potentially strengthening T-cell-mediated anti-tumor responses." (PMID 41180485, 2025).